ALK (ALK receptor tyrosine kinase)
Diseases named in the same sentence as ALK in open-access papers (continued):
Sharing a sentence is not in itself a finding about the gene and the disease.
tumor (continued). "As well, metastatic tumor cells were found in 5/19 lymph nodes and were positive for ALK on immunohistochemical staining." (PMID 28923119, 2017). "One patient with ALK gene abnormality showed weak expression of PD-L1 on 2% of tumor cells in IHC staining with SP142 antibody." (PMID 28969070, 2017). "The high homology between ROS1 and ALK renders ROS1-rearranged tumours sensitive to several ALK inhibitors." (PMID 29225694, 2017). "In fact, out of a priority-ranked list of 75 tumor antigens evaluated by the National Cancer Institute for cancer vaccine development, ALK ranked fourth." (PMID 29190913, 2017). "Baseline characteristics of patients including gender, age, smoking history, tumor differentiation and stage were balanced matching between KRAS mutation group and EGFR/ALK/KRAS wild-type group by propensity matching score analysis." (PMID 28451792, 2017). "For example, ALK autoantibodies can be detected from patient serum, and pretreatment ALK antibody titers are inversely correlated with stage of disease, amount of circulating tumor cells, and cumulative incidence of relapse." (PMID 29190913, 2017). "Tumor gDNA from patients 5, 7 and 8 also revealed ALK diploid status, however, corresponding plasma-derived cfDNA indicated an ALK gain in these patients." (PMID 29156716, 2017). "The aims of this project are to induce a strong immune response against ALK in DNA electrovaccinated mothers in order to transfer anti-tumor immunity to their cancer-prone offspring." (PMID 28763018, 2017). "IHC analysis indicated that the tumor cells were positive (2+ staining) for the ALK antibody (Histofine ALK iAEP Detection Kit; Nichirei Bioscience Inc., Tokyo, Japan)." (PMID 28683775, 2017). "Copy numbers assessed using cfDNA indicated a gain for MYCN in 2 patients (1 and 4) and for ALK in 3 patients (5, 7 and 8), whereas corresponding tumor gDNA revealed normal diploid status." (PMID 29156716, 2017). "This small-molecule inhibitor shows specificity against c-Met and anaplastic lymphoma kinase (ALK) and reduced mouse tumor size paralleled by increased animal survival." (PMID 28212658, 2017). "Validation analysis of candidate miRNAs suggested also miR-503-5p as being significantly deregulated between ALK+ and ALK- NB cell line and tumor subgroups." (PMID 28915608, 2017). "The true therapeutic benefit of molecular targeted therapy in NSCLC patients with ALK fusion protein relies on identifying the right patient population for treatment and detecting the emergence of tumor resistance." (PMID 29312572, 2017). "We have also demonstrated that NPM/ALK modulates the tumor microenvironment, including the stimulation of angiogenesis." (PMID 28771164, 2017). "The anaplastic lymphoma kinase (ALK) is recognized by the immune system as a tumor antigen, and preclinical evidence suggests that ALK-rearranged NSCLCs can also be successfully targeted immunologically using vaccine-based approaches." (PMID 29190913, 2017). "DUSP22 has a tumor suppressor function in B-cell lymphomas, T-lymphoblastic leukemias and ALK positive ALCLs." (PMID 28061468, 2017). "Both cases were positive for ALK fusion in both tests, and ALK fusions were present in the major population in the tumor." (PMID 28472989, 2017). "RT-PCR is a sensitive and rapid detection assay when compared to FISH for the detection of ALK in NSCLC tumor samples." (PMID 28763012, 2017). "We confirmed that tumour cells with ALK gene translocations contained enhanced metastatic potential and acquired the metastatic phenotype." (PMID 28887531, 2017). "Both were identified as an ALK-fusion partner from NSCLC tumor samples and the two proteins also fuse with the intracellular domain of ALK." (PMID 28805682, 2017). "In this study, we applied Ventana ALK D5F3 IHC to investigate the heterogeneity of ALK gene translocations in excision specimens and compared the ALK status between primary tumours and their corresponding metastatic lymph nodes." (PMID 28887531, 2017).
tumor (continued). "We concluded that ALK-positivity is correlated with worse disease-free, tumor-specific, and overall survival." (PMID 29156778, 2017). "We detected ALK gains in 4 plasma samples, one of which was confirmed in the corresponding tumor sample." (PMID 29156716, 2017). "The tumour cells were positive for B-lineage markers including Oct-2 and Bob-1 as well as ALK in all cases, while a large proportion of cases were positive for plasma cell markers including CD38, CD138, MUM1 and VS38C (more than 75%)." (PMID 28665943, 2017). "Both FISH and IHC are widely used in clinical laboratories for the detection of ALK rearrangements in NSCLC tumor samples." (PMID 28763012, 2017). "Anaplastic lymphoma receptor tyrosine kinase (ALK) translocations are found in several tumor types, and are an important target for treatment with ALK inhibitors in patients with non-small cell lung cancer." (PMID 29084941, 2017). "The protein products of the SHP1, STAT5A and ILR2γ genes act as tumor suppressors by interfering with the expression of NPM/ALK." (PMID 28771164, 2017). "As an example, for FISH analysis, the FDA recommended counting at least 50 tumor cells for ALK status assessment, and if 15–25 cells demonstrated an ALK rearrangement, an additional 50 tumor cells have to be counted by another pathologist." (PMID 28805682, 2017). "Many different ALK mutations occur and can be detected by NGS analysis with free circulating tumor DNA." (PMID 28805673, 2017). "Inhibition of ALK activity resulted in sustained tumour regression in a xenotransplant tumour model." (PMID 28665943, 2017). "We further demonstrated that this pathology-determined OS can be affected by both tumor stage and status of oncogenic mutations in EGFR, KRAS, ALK, RET, and BRAF genes." (PMID 29137260, 2017). "Mice prophylactically treated with vaccine were protected from developing lung tumors after being challenged with ALK-positive tumor cells." (PMID 29190913, 2017). "By examining the ALK status in the primary tumours and corresponding metastatic tumours in our series, we propose that ALK gene translocation is a stable genetic alteration once it has occurred." (PMID 28887531, 2017). "Fifty three patients (53/196, 27%), including 37 ALK-positive cases and 16 ALK-negative cases, with paired primary tumours and lymph node metastases samples were further investigated for concordance of ALK status." (PMID 28887531, 2017). "On immunohistochemistry, tumor cells were positive for vimentin, smooth muscle actin, ALK and showed focal positivity for desmin and CD34 but were negative for pan-cytoceratin, CD117, DOG-1, S-100, h-caldesmon, CD21, CD23 and CD30." (PMID 28923119, 2017). "Immunohistochemically detecting ALK-positive tumor cells in lymph nodes is a reliable way to verify IMT metastasis." (PMID 28923119, 2017). "The resulting ALK fusions, such as EML4-ALK, showed responsiveness of ALK-positive tumours to ALK TKIs." (PMID 29225694, 2017). "A response evaluation criteria in solid tumors (RECIST) partial response was observed by the seventh month of ALK inhibition and the tumor remained in control for 14 months." (PMID 28409069, 2017). "A potential alternative strategy for treating ALK-positive cancers is to exploit the natural immune responses against tumor cells expressing ALK protein." (PMID 29190913, 2017). "There was perfect concordance for ALK status between CTC and tumor samples: ALK rearrangement was detected in CTCs and tumor samples in five patients (6%), whereas both CTC and tumor samples were negative in the remaining 82 patients." (PMID 29312651, 2017). "Data showed that ALK rearrangement patterns (majority 1F1R1G) observed in primary tumor tissues were recapitulated on most of the ALK-positive CTCs, giving an overall concordance rate of over 90% based on the 1F1R1G fusion pattern." (PMID 26993609, 2016).
tumor (continued). "A total of 25 tumour tissues with activating EGFR mutations L858R (n=12) and E19 deletions (n=10) as well as activating ALK fusions (n=3) and matching control tissue were selected for comparative analysis." (PMID 27409166, 2016). "NGS testing results (Foundation Medicine, Inc., MA) indicated that the tumor was ALK-rearrangement positive for EIF2AK3-ALK fusion, and the patient received crizotinib treatment for 19 months." (PMID 27480287, 2016). "Seven fusion gene products were identified in these three tumor samples, including an ALK fusion gene in each patient." (PMID 27045755, 2016). "Hierarchical clustering of ALK+ versus CD3+ cells (31,580 CpG sites) resulted in a distinct ALK+ cluster (except for one tumor) that appeared more distant to ALK− and CD3+ T cell samples because of a higher number of hypomethylated MVPs in ALK+ tumors." (PMID 27705804, 2016). "For example, NPM-ALK has been shown to induce promoter DNA methylation of tumor suppressors via its downstream target STAT3, which is also a highly relevant TF in ALK− ALCL." (PMID 27705804, 2016). "Among the 34 FISH-negative cases, 33 resulted not translocated by our method, while one sample was clearly detected as translocated (Case ID #19, 3′ ALK positivity of 58.6%; 95% CI: 47–73.5), despite its scarce tumor cellularity (5%)." (PMID 27206799, 2016). "Crizotinib, an oral ALK inhibitor, has been shown to be an important inhibitor of tumor growth and survival that reduces or slows tumor growth." (PMID 27322143, 2016). "Genetic aberrations in anaplastic lymphoma kinase (ALK) have recently generated interest in developing targeted therapies due to their role in tumor growth." (PMID 26838801, 2016). "A study showed combined treatment of crizotinib and an mTOR inhibitor led to reduced tumor growth and prolonged survival in ALK F1174L/MYCN-positive models compared to single agent treatment." (PMID 26786851, 2016). "The mechanism that explain this situation is important; in fact, there are different subclonal ALK-positive malignant tumour cells (MTC) that contribute to ‘tumour mosaicism’." (PMID 27433281, 2016). "All these biomolecular features of resistance are the core to understand the right and powerful strategy to treat patients after the failure of first hit inhibition on ALK positive tumours." (PMID 27433281, 2016). "Immunohistochemically, the spindle tumor cells show variable staining for smooth muscle actin, desmin, and ALK." (PMID 26762155, 2016). "The tumor from Patient P5 presented various ALK rearrangement patterns such as 1F1R1G, 2F1R, 2F2R, 1F1R and 1F2R." (PMID 26993609, 2016). "In a first report, one-fourth of the total 177 CTCs of one patient harbored ALK rearrangements and in the other, 100% of the CTCs of 5 patients were ALK-rearranged, whereas in the primary tumor tissue this was around 50% in both studies." (PMID 26980749, 2016). "Immunoblotting analysis of tumor material revealed decreased phospho-ALK levels in the brigatinib treated group, in line with our earlier findings." (PMID 27049722, 2016). "FDA and EMA, for example, licensed the use of crizotinib for first line treatment and ceritinib and alectinib (currently US FDA and Japan) for intolerant or resistant to crizotinib ALK-positive tumours." (PMID 27433281, 2016). "We first determined the best number of z-stacks to scan filter enriched-CTCs from patients with an ALK-rearranged tumor." (PMID 27417942, 2016). "Overall, our data suggest a probable role of ALK in tumor progression and metastasis of pediatric RMS." (PMID 27385213, 2016). "The studies measured mRNA level of thymidylate synthase (TS), one of the catalytic enzymes thought to reduce sensitivity to pemetrexed, and showed a significantly lower TS mRNA level in ALK-rearranged tumor cells." (PMID 27756333, 2016).
tumor (continued). "Of the 16 ALK-positive cases, nine displayed strong homogeneous positivity in more than 75 % of tumor cells, while strong staining in 1–40 % of tumor cells was observed in the remaining seven tumors." (PMID 27495736, 2016). "ALK-positive patients were more likely to have a small tumor (≤ 3 cm), compared to EGFR-positive patients, although this difference was not statistically significant (p = 0.06)." (PMID 27518729, 2016). "Circulating tumor cells (CTCs) released from the primary tumor site into the circulation represent a potential means of non-invasively isolating tumor cells for ALK FISH testing and other molecular characterizations." (PMID 26993609, 2016). "She received crizotinib from November 2011 based on an ALK-positive FISH in the primary tumor sample and had a near complete response." (PMID 27045755, 2016). "The high crossover rate and the high sensitivity of ALK-positive tumours to pemetrexed containing chemotherapy accounted for this impressive performance of chemotherapy arm." (PMID 27433281, 2016). "In this study we examined the therapeutic potential of a novel ALK inhibitor, entrectinib, in obliterating NB tumor cells." (PMID 26735175, 2016). "In this study, we compared various ALK –FISH patterns to next –generation sequencing (NGS) for gene fusion detection, ALK immunohistochemistry (IHC) and tumor responses to crizotinib." (PMID 27769042, 2016). "25% of the total 177 CTC of 1 patient harbored ALK-gene rearrangements, and 54% of the 200 primary tumor cells did." (PMID 26980749, 2016). "We further demonstrate an ALK phosphorylation by IHC of this rearranged case, indicative of a possible response to specific small molecule inhibitors, as reported in other tumor types." (PMID 27385213, 2016). "Following FISH testing on all tumor samples in the cohort, it was found that ALK-positive tumors harbored ALK rearrangements with various patterns of abnormality." (PMID 26993609, 2016). "Correlating with these findings, there was a significant correlation between the expression of active β-catenin and MYC in ALK + ALCL primary tumor cells." (PMID 27821172, 2016). "At present, when ROS1 testing is required, it will be reasonable to test the same tumours currently being selected for EGFR mutation and ALK gene rearrangement." (PMID 27535289, 2016). "Tumor EGFR mutation, KRAS mutation and ALK rearrangement status were available for 124 (72.5 %), 126 (74 %), and 167 (98 %) patients, respectively." (PMID 27422280, 2016). "PI3K/AKT/mTOR and JAK/STAT are the most important signaling pathways downstream of ALK and play an important role in cell growth in many tumor types." (PMID 26786851, 2016). "Generally, primary tumours and metastatic lesions are equally suitable to determine ALK status for treatment selection." (PMID 27433281, 2016). "As shown in a patient with ALK-rearranged tumor, a maximal number of FISH spots was detected at a step of 0.6 μm (92 % detection rate)." (PMID 27417942, 2016). "The advent and application of specific ALK inhibitors have significantly improved the clinical outcome of patients with ALK+ tumours, which include (most notably) ALK+ALCL and ALK+ lung cancers." (PMID 27641368, 2016). ""Patients with EGFR or ALK genomic tumor aberrations should have disease progression on FDA-approved therapy for these aberrations prior to receiving nivolumab," said Ms." (PMID 29152394, 2016). "Patients should have tumor tissue assessed for the presence of a driver mutation, such as mutated epidermal growth factor receptor (EGFR) or the anaplastic lymphoma kinase (ALK) fusion oncogene." (PMID 28090370, 2016). "CTCs and tumor sections both showed ALK rearrangement as well as complex signal patterns, as evidenced by the multiple probe rearrangements and polysomy in the nuclei." (PMID 27739521, 2016).
tumor (continued). "Due to the high similarity of promoter DMRs in ALK+ and ALK− samples, we used the significant 194 hypomethylated and 186 hypermethylated overlapping promoters from both tumor subgroups." (PMID 27705804, 2016). "Crizotinib induces rapid tumor regression and objective responses in the majority of patients with ALK-positive tumors." (PMID 29282427, 2016). "Transgenic ALKF1174L mice were dependent on ALKF1174L activity as treatment with ALK inhibitor TAE684 induced a complete tumor regression." (PMID 27655666, 2016). "The authors attributed the observed differences in ALK status to the existence of different cell populations within the tumor." (PMID 26968843, 2016). "ALK FISH testing in formalin-fixed, paraffin-embedded (FFPE) NSCLC tumor tissues has a ‘false positive’ cutoff value of 15% to allow for the best separation between ALK-rearranged and ALK wild-type cells." (PMID 26993609, 2016). "Second-line therapy was given according to CWS-2012 relapse protocol and based on the proven ALK-positivity of the tumor, ALK inhibitor crizotinib was permitted as an off-label drug for maintenance therapy for 10 months." (PMID 27756397, 2016). "This resistance mechanism is also named ‘ALK-dominant’, which means that these kind of tumours maintain ALK as a gene drive to addition." (PMID 27433281, 2016). "This novel combination thus represents a viable strategy for the treatment of resistant ALK+ neoplasms." (PMID 27793034, 2016). "The assay is considered to be positive for ALK rearrangement if at least 15% of tumor cells show rearrangement." (PMID 27769042, 2016). "The abrogation of ALK phosphorylation in the excised tumor indicates that brigatinib does indeed block ALK activity within the tumor." (PMID 27049722, 2016). "While Crizotinib, an ALK inhibitor, has been found to be therapeutically useful against a subset of ALK+ tumours, clinical resistance to this drug has been well recognized and the mechanism of this phenomenon is incompletely understood." (PMID 27641368, 2016). "A planned phase Ib dose-expansion cohort at the recommended phase II dose (RP2D) was conducted to evaluate the tumor response of ASP3026 in patients with metastatic ALK-positive NSCLC who progressed on crizotinib." (PMID 26966027, 2016). "In Patient P5, the CTCs were able to recapitulate three out of five ALK rearrangement patterns observed in the tumor tissue." (PMID 26993609, 2016). "As exemplified by the HOXD cluster, we detected DNA hypermethylation at all four clusters and additional homeobox genes in ALK+ and ALK− ALCL tumor samples." (PMID 27705804, 2016). "Nevertheless, ALK can be both detected as a fusion protein kinase or full length receptor protein in several tumour types where it activates a multitude of downstream signaling pathways following its own activation and phosphorylation." (PMID 27385213, 2016). "It happens in primitive tumour as well as in all metastases resulting in different mechanisms to escape the blockade to ALK TKIs." (PMID 27433281, 2016). "The analysis of updated results of phase I trial clearly showed that crizotinib is actually the best choice in patients carrying ALK positive tumours." (PMID 27433281, 2016). "After data normalization and quality control steps, we identified 42,752 and 12,354 significant methylation variable positions (MVPs) between tumor (ALK+ or ALK−) and normal control (CD3+ T cells) (based on M value calculation and adjusted p < 0.01)." (PMID 27705804, 2016). "The combined use of a MAP kinase inhibitor and ALK inhibitor resulted in robust tumor regression in the ceritinib-resistant PDX." (PMID 26802023, 2016). "These components represent crucial control points of the ALK signalling pathway and their combined targeting is likely to be of fundamental importance for efficient therapies that circumvent tumour resistance." (PMID 27669408, 2016).